E2F4 (E2F transcription factor 4)
Diseases named in the same sentence as E2F4 in open-access papers (continued):
Sharing a sentence is not in itself a finding about the gene and the disease.
meningioma (2 papers, 2020 to 2025). A generally slow growing tumor attached to the dura mater. "In brief, our study demonstrated the tumor-promoting function of SLC7A1 by regulating the transcription factors FOXM1 and E2F4 in meningioma and identified SLC7A1 as a potential therapeutic target." (PMID 41184266, 2025). "Western blot confirmed a progressive downregulation of FOXM1 and E2F4 with increasing duration of AZ628 treatment in meningioma cells." (PMID 41184266, 2025). "The results revealed a significant reduction of FOXM1 and E2F4 upon SLC7A1 knockdown in meningioma cells." (PMID 41184266, 2025). "In addition, the bulk-level GSEA analysis also demonstrated a significant upregulation of transcriptional activity for FOXM1 and E2F4 in meningioma samples from the high-SLC7A1 group compared to the low-SLC7A1 group." (PMID 41184266, 2025). "All these findings suggest that the SLC7A1-FOXM1/E2F4 regulatory axis may contribute to the malignant progression of meningioma." (PMID 41184266, 2025). "However, further research is needed to elucidate the molecular mechanisms underlying the regulation of transcription factors FOXM1 and E2F4 by SLC7A1 in meningioma." (PMID 41184266, 2025). "Interestingly, GSVA analysis at the single-cell level also revealed a significant increase in the transcriptional activity scores of FOXM1 and E2F4 in clusters 4 and 9 of meningioma cells with high SLC7A1 expression." (PMID 41184266, 2025). "The results showed that E2F4 knockdown significantly inhibited the proliferation of meningioma cells, suggesting that E2F4 may contribute to the malignant progression of meningioma." (PMID 41184266, 2025). "We also verified by CCK-8 assays that knockdown of E2F4 significantly suppresses the proliferation of meningioma cells, indicating that E2F4 may contribute to the malignant progression of meningioma." (PMID 41184266, 2025). "This further supports the E2F4/FOXM1 module as a marker of aggressiveness in meningioma." (PMID 33093491, 2020). "Furthermore, SLC7A1-FOXM1/E2F4 regulatory axis may contribute to the malignant progression of meningioma." (PMID 41184266, 2025). "RNA sequencing analysis revealed a significant decrease in the transcriptional activity of FOXM1 and E2F4 in IOMM-Lee and SZ8511 meningioma cells following SLC7A1 knockdown." (PMID 41184266, 2025). "SLC7A1 may facilitate the malignant progression of meningioma through the regulation of E2F targets, G2M checkpoint, and MYC targets pathways via the SLC7A1-FOXM1/E2F4 axis." (PMID 41184266, 2025). "Additionally, AZ628 treatment also inhibited the transcriptional activity and protein expression of FOXM1 and E2F4, mirroring the effects of SLC7A1 knockdown in meningioma." (PMID 41184266, 2025). "Furthermore, it can also be observed in the meningioma organoids that treatment with AZ628 leads to the downregulation of FOXM1 and E2F4." (PMID 41184266, 2025). "Although there is no specific research on E2F4 in meningioma, it is widely recognized as an oncogenic transcription factor in various tumors." (PMID 41184266, 2025). "FOXM1 has been identified as a key target in meningiomas; however, the role of E2F4 in meningioma has not been previously reported." (PMID 41184266, 2025). "Additionally, SLC7A1 may exert oncogenic functions in meningioma by regulating transcription factors FOXM1 and E2F4." (PMID 41184266, 2025). "Therefore, SLC7A1 may facilitate the malignant progression of meningioma through the regulation of E2F targets, G2M checkpoint, and MYC targets pathways via the SLC7A1-FOXM1/E2F4 axis." (PMID 41184266, 2025).
oral squamous cell carcinoma (2 papers, 2022 to 2023). "We aimed to evaluate the prognostic value of E2F4 expression in oral squamous cell carcinoma (OSCC) and clarify its influence on immune cell infiltration and biological functions." (PMID 36567912, 2022). "High expression of E2F4 is an unfavorable prognostic factor in oral squamous cell carcinoma." (PMID 37349788, 2023).
pancreatic adenocarcinoma (2 papers, 2020 to 2022). "In pancreatic adenocarcinoma patients, as a tumor suppressor gene, E2F4 expressions were positively correlated with the infiltration of B cells, CD8+ T cells, macrophages, neutrophils, and dendritic cells." (PMID 36567912, 2022). "In addition, ONCOMINE analysis revealed no significant contrast in the transcriptional levels of E2F2, E2F4, and E2F6 between pancreatic adenocarcinoma and normal samples." (PMID 33604289, 2020).
adenoma (1 paper, 2013). A neoplasm arising from the epithelium. "More importantly, all normal specimens analyzed (resection margins, M) presented hypophosphorylated forms of E2F4 (arrowhead) whereas all adenoma samples (A) exhibited hyperphosphorylated forms of E2F4 (arrows)." (PMID 23919615, 2013). "Adenomas displayed significantly higher expression levels of E2F4 in comparison to their corresponding benign epithelium (margin)." (PMID 23919615, 2013). "Interestingly, E2F4 expression was mostly detected in the nucleus and appeared to be phosphorylated in adenomas." (PMID 23919615, 2013).
anaplastic thyroid cancer (1 paper, 2020). "In anaplastic thyroid cancer (ATC), E2F4 overexpression inhibits the transcription of the TTK in ATC cells." (PMID 33292231, 2020).
androgen excess (1 paper, 2025). "The Inhba/Smad2/E2f4 axis contributes to thecal cell hyperplasia and androgen excess in PCOS, and may serve as a mechanistic entry point for further investigation into the regulation of TCs proliferation in this disorder." (PMID 40831751, 2025).
autoimmune disease (1 paper, 2018). A disorder resulting from loss of function or tissue destruction of an organ or multiple organs, arising from humoral or cellular immune responses of the individual to their own tissue constituents. "Antimetabolites are a class of drugs used for inducing medical abortions and treating cancers and autoimmune diseases through halting of cell cycles, while E2F1 and E2F4 are well-known regulators of cell cycles." (PMID 29325558, 2018).
cervical tumour (1 paper, 2020). "Moreover, RT‐qPCR was conducted, and the enhanced expression of C16orf74 was detected in the tumours with HAND2‐AS1 overexpression and E2F4 silencing or C16orf74 overexpression (P < .05), further supporting the critical role of C16orf74 expression in the cervical tumour growth." (PMID 32314545, 2020).
ciliopathies (1 paper, 2017). "Thus, E2f4 integrates nuclear and previously unsuspectedcytoplasmic events of centriole amplification, providing new perspectives for theunderstanding of normal ciliogenesis, ciliopathies and cancer." (PMID 28675157, 2017).
colorectal adenoma (1 paper, 2013). An adenoma that arises from the colon or rectum. "Of note, the MEK/ERK and GSK3 signaling pathways, shown herein to be implicated in the regulation of E2F4 phosphorylation and localization, are known to be involved in colorectal adenoma formation." (PMID 23919615, 2013). "Finally, we show that E2F4 is overexpressed, phosphorylated and localized in the nucleus of epithelial cells from colorectal adenomas exhibiting APC and KRAS or BRAF mutations." (PMID 23919615, 2013). "Finally, E2F4 was found to be overexpressed, phosphorylated and nuclear localized in epithelial cells from human colorectal adenomas exhibiting mutations in APC and KRAS or BRAF genes, known to deregulate GSK3/β-catenin and MEK/ERK signaling, respectively." (PMID 23919615, 2013). "We therefore verified the protein status of E2F4 in human colorectal adenomas." (PMID 23919615, 2013).
embryonal carcinoma (1 paper, 2013). A non-seminomatous malignant germ cell tumor characterized by the presence of large germ cells with abundant cytoplasm resembling epithelial cells, geographic necrosis, high mitotic activity, and pseudoglandular and pseudopapillary structures formation. "Consistent with the recent description of a DREAM-like complex in embryonal carcinoma F9 cells, we find that LIN9 associates with the other core-subunits of DREAM and with B-MYB, but not with pocket proteins or E2F4 in ESCs." (PMID 23667535, 2013).
emphysema (1 paper, 2017). "Furthermore, E2F4 has been found to form a complex with EGR-1 (a highly significant transcription factor in ECLIPSE and LT-CDNM) in response smoke exposure, which may lead to autophagy, apoptosis and subsequently to development of emphysema." (PMID 29237467, 2017).
fatty liver disease (1 paper, 2023). A reversible condition wherein large vacuoles of triglyceride fat accumulate in liver cells via the process of steatosis. "Notably, previous studies have linked NRF1 inactivation to the development of nonalcoholic steatohepatitis, while YY1 upregulation has been associated with fatty liver diseases, whereas E2F4 was found to promote HCC proliferation." (PMID 37627157, 2023).
gastric adenocarcinoma (1 paper, 2021). "In gastric adenocarcinoma which has frequent microsatellite instability, mutations of E2F4 are integral multiples of three nucleotides lost or gained." (PMID 34532281, 2021).
liposarcoma (1 paper, 2021). A usually painless malignant tumor that arises from adipose tissue. "It has been reported that high E2F1 or E2F4 activity in liposarcoma patients is associated with unfavorable prognosis, with the core target gene sets of E2F1 containing 116 genes and the core target gene sets of E2F4 containing 199 genes, among which only 21 are shared." (PMID 34532281, 2021).
liver disease (1 paper, 2023). "Using novel approaches, we elucidated the potential of miR-122 in modulating key transcription factors such as NRF1 and E2F4, which are intrinsically linked to liver disease." (PMID 37627157, 2023). "Firstly, through transcriptome analysis of polyribosome-bound RNAs, we discovered that miR-122 exhibits potential antagonistic effects on specific transcription factors known to be dysregulated in liver disease, including nuclear respiratory factor-1 (NRF1) and the E2F transcription factor 4 (E2F4)." (PMID 37627157, 2023).
lymph node metastasis (1 paper, 2022). "The expression of E2F4 is associated with lymph node metastasis in TNBC patients." (PMID 36567949, 2022).
male infertility (1 paper, 2017). The inability of the male to effect fertilization of an ovum after a specified period of unprotected intercourse. "The male infertility observed in mice lacking both E2F4 and E2F5 has been proposed to result due to defects solely in the development of MCCs in the ED and future work will be needed to fully characterize this defect in Ccno-/- mice." (PMID 29245899, 2017).
metastatic disease (1 paper, 2025). "Here, degree centrality scoring in the high metastatic cluster gene regulatory network configuration successfully recognised key TFs associated with metastatic disease, such as SP1 and E2F4." (PMID 39748426, 2025).
myeloid leukemia (1 paper, 2024). A clonal proliferation of myeloid cells and their precursors in the bone marrow, peripheral blood, and spleen. "For this, we extracted the lists of DEGs in Tfdp1-KO mouse HSPCs, E2f4-KO mouse embryonic stem cells (ES cells; GSE109684), and TFDP1-KO human HAP cells (myeloid leukemia cell line; GSE144453)." (PMID 39043964, 2024).
neuroblastoma (1 paper, 2022). Neuroblastoma (NB) is the most common solid, extracranial childhood tumor. "E2F4 was associated with the event free survival of neuroblastoma in TARGET, GSE16476, GSE85047 and E-MTAB-1781 datasets." (PMID 35764946, 2022). "E2F4 was associated with the overall survival of neuroblastoma in TARGET, GSE16476, GSE85047 and E-MTAB-1781 datasets." (PMID 35764946, 2022).
oral cancer (1 paper, 2019). "The genome wide transcription factor enrichment profile from ENCODE repository revealed a few prospective TF candidates for regulation of CARM1 expression in oral cancer such as E2F4, CTCF, YY1 and cMyc etc.." (PMID 31217904, 2019).
osteoporosis (1 paper, 2022). A condition of reduced bone mass, with decreased cortical thickness and a decrease in the number and size of the trabeculae of cancellous bone (but normal chemical composition), resulting in increased fracture incidence.
otitis media (1 paper, 2014). Inflammation of the anatomical structures of the middle ear, which is most often caused by an infectious process. "Previous candidate gene studies associated a number of immune system genes with otitis media, which included TNF-α, IL-6, IL-10, Tlr4, surfactant, CD14, FcγRIIa, IFNγ, Eya4, p73, MyD88, Fas, E2f4, Plg, Fbxo11, and Evi1." (PMID 24466073, 2014).
plasmacytoma (1 paper, 2009). Plasmacytoma is a localized mass of neoplastic monoclonal plasma cells that represents approximately 5% of all plasma cell neoplasms. "Three more E2f4−/− tumors, all with the late morphological phenotype, clustered alongside a group of wild type tumors that overexpress genes characteristic of plasmacytomas." (PMID 19749980, 2009).
preeclampsia (1 paper, 2025). Preeclampsia is a hypertensive disorder of pregnancy that is characterized by new-onset hypertension with proteinuria presenting after 20 weeks of gestation, and depending on mild or severe forms may initially present with severe headache, visual disturbances, and hyperreflexia. "However, the promoter binds the E2F4 transcription repressor, which is upregulated in preeclampsia via the activated HIF1A/TGFB3 axis." (PMID 41167398, 2025).
rectal cancer (1 paper, 2017). A primary or metastatic malignant neoplasm that affects the rectum. "The results showed that E2F4 and SP3 correlated significantly with POFUT1 and PLAGL2 in colon and rectal cancer, which indicated E2F4 and SP3 are the most likely transcription factor binding to this bidirectional promoter and causing co-expression of the gene pair." (PMID 29108255, 2017).
small cell lung carcinoma (1 paper, 2010). Small cell lung cancer (SCLC) is a highly aggressive malignant neoplasm, accounting for 10-15% of lung cancer cases, characterized byrapid growth, and early metastasis. "Studies from E2F4 (−/−) Rb (−/−) chimeric mice have suggested that E2F4 may play a role in early stages of small cell lung cancer." (PMID 20421925, 2010).
Stroke (1 paper, 2022). Sudden impairment of blood flow to a part of the brain due to occlusion or rupture of an artery to the brain. "E2F family members (E2F1 and E2F4) are involved in the regulation of CITED2 expression in neurons after stroke-related injury." (PMID 36358994, 2022).
teratocarcinoma (1 paper, 2013). A germ cell tumor characterized by the presence of an embryonal carcinoma component and a teratoma component. "They reported that human stem cells and teratocarcinoma cells show a selective reduction in the expression of E2F1, E2F2, E2F3 and p105 (encoded by NFKB1) and enhanced expression of E2F4, E2F5, E2F6 and p130 (encoded by RBL2) compared with human normal somatic IMR90 cells." (PMID 24355041, 2013).
Xeroderma pigmentosum complementation group C (1 paper, 2022). "Finally, E2F4 has also been implicated in NER since the p130/E2F4 complex controls the expression of xeroderma pigmentosum complementation group C, a protein that serves as the primary initiating factor in the global genome NER pathway." (PMID 36292945, 2022).
tumor (86 papers, 2006 to 2026). "Many completed studies in recent years focused on the association between the expression of the E2F4 transcription factor in tumor tissues and the clinical characteristics of tumors." (PMID 35840663, 2022). "From the analysis of GEO and TCGA data, E2F4 expression was found to be up-regulated in HNSCC tumor tissues, and its level was associated with T, Grade, and M staging." (PMID 35840663, 2022). "Next, we evaluated if E2F4 expression was associated with tumor immune status across 32 solid cancer types." (PMID 33613768, 2021). "We suggest that the Myc transgene fails to overcome the inefficient developmental progression of the B lineage in E2f4-deficient mice, there is a reduced number of susceptible progenitor cells, and consequently delayed tumor emergence." (PMID 19749980, 2009). "Furthermore, a close association of E2F4 with degree of differentiation and T stage of a tumor was found by analyzing the clinical data of patients." (PMID 35840663, 2022). "Next, we evaluated if E2F4 expression was associated with tumor immune status in HNSCC." (PMID 35840663, 2022). "The association between E2F4 expression and tumor infiltration of immune cells was analyzed." (PMID 35840663, 2022). "In contrast, tumor growth is enhanced by the downregulation of inhibitory E2F transcription factors such as E2F4 and E2F7, and such an imbalance may cause a switch from cell quiescence to growth promotion." (PMID 31929759, 2020). "The mechanism by which LOH 16q increases the recurrence risk in WT may involve the effects of LOH 16q on certain tumor-associated genes such as E2F4, COX4, and CTCF." (PMID 29029528, 2017). "Antisense oligonucleotide-mediated inhibition of SNRPF disrupts this feedback loop, downregulates DDX24 and E2F4 via IR, and significantly impairs tumor growth in vitro, in vivo, and in patient-derived xenografts." (PMID 42107058, 2026). "In our experimental system, suppression of E2F4 expression translated into a dramatic enhancement of the in vivo anti-tumor activity of irinotecan, across multiple pre-clinical models of human CRC." (PMID 39896677, 2025). "The specificity of E2F4 condensate staining was confirmed with E2F4-KD tumor cells and with isotype control IgG in patient samples." (PMID 41249116, 2025). "E2F4, a member of the E2F family, is a strong transcriptional inhibitor and regulates differentiation and cell cycle arrest by increasing tumor growth." (PMID 41007338, 2025). "Mechanistically, SNRPB2 stabilized E2F4 protein by preventing its proteasomal degradation, and E2F4 overexpression reversed the tumor-suppressive effects of SNRPB2 silencing." (PMID 40612943, 2025). "Conversely, WT tumor cells showed leading proliferation-promoting TFs (E2F4 and ETV4), aligning with rapid cell cycle advancement and glycolytic reprogramming." (PMID 41430036, 2025). "Violin plots demonstrated significantly elevated activities of IRF5, IRF8, KLF2, TFAP2B, and MAFK in Zbp1−/− tumor cells, while E2F4 and ETV4 were preferentially activated in WT tumors." (PMID 41430036, 2025). "In the E2F4 knockdown model, E2F4 was confirmed to contribute to tumor malignancy features, including tumor growth and motility." (PMID 40560737, 2025). "We next expressed E2F4-GFP in Py8119 tumor cells, and consistent formation of condensates was observed." (PMID 41249116, 2025). "In TNBC patients (NCT03197389), tumor cells with lower E2F4 expression presented a stronger antigen presentation signature, highlighting the possibility that E2F4 promotes immune evasion." (PMID 41249116, 2025). "Significantly lower levels of nucleus-localized E2F4 were observed in both mouse tumor cells and TNBC patient samples with condensates." (PMID 41249116, 2025).